NES (nestin)
Diseases named in the same sentence as NES in open-access papers (continued):
Sharing a sentence is not in itself a finding about the gene and the disease.
tumor (continued). "In addition, we found that the Classical markers FGFR3, PDGFA, EGFR, AKT-2 and Nestin are highly expressed in intracranial tumor tissue derived from bulk tumor cells and Sp-GSCs, while there is lower expression in Ad-GSC intracranial tumors." (PMID 25955030, 2015). "Nestin staining allowed the comparison of tumor cell infiltration." (PMID 26700636, 2015). "In order to investigate, if Nestin-expression might serve as novel and selective marker for newly formed tumor blood vessels, we analyzed angiogenic vessels in tumor specimen from cancer patients." (PMID 25019063, 2014). "Given the association between high nestin expression and elevated staining for the proliferative cell markers, Ki-67 and PCNA, we focused on the role of nestin in tumor cell proliferation using retroviruses to introduce shRNA vectors with nestin-targeting (or control) sequences into NSCLC cells." (PMID 24498263, 2014). "Tumor sections were immunostained for Nestin, βIII-Tubulin and GFAP." (PMID 25121761, 2014). "Nestin was expressed in most cancer specimens and all the tumor cell lines analyzed." (PMID 24498263, 2014). "In summary, we observed nestin-positive tumor cells in a portion of ESCC samples in Chinese population and demonstrated a significant association of nestin expression with the subset of Chinese ESCC patients displaying poor outcomes and high levels of proliferative markers." (PMID 24966803, 2014). "To determine whether tumor cell proliferative inhibition is related to cell cycle regulation, we investigated the effects of nestin knockdown on cell cycle progression in cancer cells." (PMID 24498263, 2014). "The right portion of the tumor stained positively for collagen type II and the left portion contained neuron-like cells by H&E staining with weak to moderate staining for nestin (70%), βIII-tublin (10%) and GFAP (60%)." (PMID 24670249, 2014). "Nestin is a stem cell marker expressed by many types of cells during development while vimentin is expressed in mesenchymal cells and involved organogenesis, wound healing and tumor invasion." (PMID 24489858, 2014). "Dissociated neurospheres generated from MZ-294 cells were stained for CD133 and nestin and were shown to preferentially express these stem cell markers indicating that the cells in the 3D tumour model display more undifferentiated properties compared to the MZ-294 monolayer." (PMID 24213561, 2014). "Furthermore, DNA synthesis in nestin knockdown tumor cells was significantly inhibited compared with that in control tumor cells." (PMID 24498263, 2014). "Nestin-expressing host cells with stellate morphology were also prominently observed in close proximity to tumor cells; nestin expression sometimes overlapped with vascular (lectin) stain (not shown), suggesting a possible role of nestin-positive host cells in tumor vasculogenesis." (PMID 25051370, 2014). "In addition, treatment with HD-POL5551 alone or in combination with mcr84 had a widespread effect on the shape and size of tumor cell nuclei and appeared to reduce the numbers of nestin-positive perivascular cells (asterisks)." (PMID 25238146, 2014). "Therefore, Nestin expression correlates with angiogenesis because it is expressed in proliferating vascular endothelial cells of the tumor." (PMID 25364727, 2014). "For this, we first examined Nestin-expression in human tumor specimen." (PMID 25019063, 2014). "Based on the data that the nestin phenotype is closely correlated with ESCC cell proliferation and apoptosis, by extension, our results suggest an association with metastasis, consistent with recent reports that tumor cells with high expression of nestin more readily metastasize." (PMID 24966803, 2014). "Since the normal basal layer of epithelium was c-kit positive like the neoplastic component, we suggest that this tumor could derive from pluripotent-like cells, also with the support of high positivity for nestin, CD133, and CD44." (PMID 24959179, 2014).
tumor (continued). "Moreover, examination of tumor boundaries in Nestin-stained samples revealed that cells of T+I− tumors infiltrated the adjoining brain, whereas tumors in the other three conditions had well-defined borders with apparently no infiltrating tumor cells." (PMID 25275602, 2014). "Nestin expression in tumor cells was detected in both the cytoplasm and nucleus." (PMID 24966803, 2014). "Cytoplasmic nestin expression in tumor cells was observed in 13 of 93 patients (14.0%)." (PMID 24785714, 2014). "However, nestin expression was also reported in developing skeletal myoblasts, detected in endothelial cells during reparative angiogenesis and tumour vascularisation, upregulated in the infarcted heart and identified in diverse forms of cancer." (PMID 25139503, 2014). "Anti-tumor activity was associated with significant changes in tumor cell proliferation and apoptosis, and a reduction in the numbers of perivascular cells expressing the TIC marker nestin." (PMID 25238146, 2014). "Nestin expression was significantly associated with those of the proliferative markers, Ki-67 (r = 0.795, P<0.001) and PCNA (r = 0.764, P<0.001), indicative of a role in tumor cell proliferation." (PMID 24498263, 2014). "In contrast, anti-nestin labeling resulted in widespread immunoreactivity in most tumor areas." (PMID 24086629, 2013). "Furthermore, tumor cells exhibiting CSCs-like features correlated significantly with Nestin staining in the invasive front." (PMID 23424657, 2013). "Notably, both OCT4 and Nanog expression were predominantly observed in tumor cells at the invasive front, and correlated strongly with Nestin expression." (PMID 23424657, 2013). "Therefore 3 of 3 Oct4/GFP and Nestin/GFP cells demonstrated ability to initiate tumor growth greater than Vector/GFP, Sm22/GFP, and GFP (−) controls." (PMID 24160469, 2013). "Nestin expression was seen in all tumor blood vessels covering the endothelial surface." (PMID 22539956, 2012). "Neoplastic transformation up-regulates Nestin expression in astrocytes of the adult CNS, suggesting that its reactivation may relate to tumor genesis." (PMID 22995409, 2012). "However, in high-generation xenografts, staining for host nestin highlighted all tumor blood vessels with a sharply defined endothelium-specific labeling pattern comparable to labeling with the endothelial marker, von Willebrand factor (data not shown)." (PMID 22539956, 2012). "Such investigation could reveal information regarding whether nestin-positive host cells proliferate at a distant site and then migrate to the tumor or whether a few of such host cells first migrate and then proliferate in the tumor context." (PMID 22539956, 2012). "Moreover, the abundance of CD133+ niches and nestin+ niches increases significantly as tumor grade increases." (PMID 22973309, 2012). "Mouse nestin-positive blood vessels in the tumor were GFAP-negative (inset)." (PMID 22539956, 2012). "Indeed, the endothelial cell marker CD31 has been found co-expressed with nestin in the tumor vasculature of orthotopic xenografts of the pancreas in the nestin-GFP mice." (PMID 22539956, 2012). "At the tumor border, the vast majority of nestin-positive cell bodies also expressed GFAP." (PMID 22539956, 2012). "At high magnification, host nestin-positive cells were detected throughout the tumor, and a high density of such infiltrating cells was observed at the tumor periphery and in deeper tumor regions, where clusters of host nestin-positive cells were also observed." (PMID 22539956, 2012). "The result showed that these tumor spheres expressed Nestin, a marker of NSCs." (PMID 21342503, 2011). "However, in the recurrent tumor, nestin was expressed in approximately 25% to 50% of tumor cells (up to 3+ cytoplasmic plasmalemmal expression)." (PMID 21494688, 2011).
tumor (continued). "These tumour spheroid cells retain the expression of well-known cell surface markers, including CD133, CD166, CD44, and EpCAM, as well as other stem cell-associated proteins such as NES, BMI-1, and MSI-1." (PMID 20332776, 2010). "Both tumour cells express neural stem cell markers nestin and CD133." (PMID 19568241, 2009). "Thus, we also used a human-specific nestin antibody to get a precise view of tumour cell spread in the terminal stage." (PMID 20040089, 2009). "A combined detection of Nestin/CD133 co-expression may benefit us in the prediction of aggressive nature of this tumor." (PMID 19108713, 2008). "However, there has been little published information concerning the morphology of intermediate filaments containing re-expressed nestin in human tumor cells." (PMID 16457706, 2006). "We observed that lymphatic endothelial cells expressing nestin-GFP could be visualized migrating along an RFP-expressing mesenchymal scaffold to encircle the tumor clumps, thereby supporting our hypothesis of endothelial haptotaxis and encircling lymphangiogenesis." (PMID 39669476, 2024). "Nestin could act as a novel therapeutic target for PC via tumor angiogenesis." (PMID 38454277, 2024). "Our subgroup analyses showed that the relationship between higher tumor expression of nestin and poor survival in patients with DTCs was consistent in Asian and non-Asian studies, which may suggest that the ethnicity of the patients seemed to have no significant influence on the association." (PMID 37485559, 2023). "Moreover, the evaluation of tumor sections immunostained for nestin and synaptophysin showed that GL261 parental tumors were characterized by a sharp boundary between the neoplastic mass and normal healthy parenchyma, with a more invasive pattern of growth than that observed in GL261-CIITA tumors." (PMID 36993983, 2023). "Based on this preliminary clinical finding, we hypothesized that CD105+Nestin+ cells outside the tumor front represent a subset of GSCs and using fresh tissue from tumor and peri-tumor regions, we purified the CD105+ cells by fluorescence-activated cell sorting (FACS) and characterized them." (PMID 36038950, 2022). "Nestin is a well-known intermediate filament protein family member, constituting a putative marker of stem cells in the CNS, an established cancer stem cell marker and a prognostic marker in different tumours, including breast cancer, colorectal cancer and lung cancer, among others." (PMID 35008260, 2021). "Thus, associations between the stathmin signature score and vascular markers, hypoxia scores and PD-L1 expression as well as the nestin signature score was also evident at the tumour cell level in the CCLE data, and support the results from our in-house patient cohorts and the TCGA cohort." (PMID 32076022, 2020). "In addition, nestin was detected in SCLC tumor cells from clinical specimens." (PMID 32903755, 2020). "Thus, to examine whether expression of RELAFUS is able to induce tumor formation in the adult population, we injected our lentivirus encoding for RELAFUS1 into the subventricular zone of Nestin-Cre+/−;Cag-Cas9+/+ young adult mice." (PMID 33228790, 2020). "Additionally, immunohistochemical analysis of GBM tumor tissues demonstrated that only a few integrin α10β1-expressing GBM cells (between 0‒10% in different patient samples) were co-expressed with Nestin, and even fewer of the integrin α10β1-expressing GBM cells were co-expressed with Sox2." (PMID 31027305, 2019). "In addition, nestin can also be utilized to selectively reflect the vascular density induced by the tumor, which, in turn, may influence the metastasis of tumor cells." (PMID 31675305, 2019). "Nestin might participate in neovascularization through cytoskeletal changes promoted by the interaction between cancer cells with stem cell properties and endothelial cells lining blood vessels in the tumor stroma." (PMID 30819139, 2019).
tumor (continued). "We observed that animals receiving Nintedanib in early stages of tumor growth displayed a significant decrease in the newly formed vessel density, although animals treated with the drug later in angiogenesis also displayed a substantial decrease in Nestin expression." (PMID 29934570, 2018). "In addition, we analyse different tumour types to reveal that nestin is not a specific marker of tumour-associated EC, and its expression level is not an independent prognostic factor." (PMID 30279450, 2018). "Again, we used nestin, Sox2, βIII-tubulin and S100β to assess the cell differentiation state and found all tissues exhibited relatively high numbers of cells expressing nestin and S100β, but low numbers of cells expressed βIII-tubulin and Sox2, as expected for this type of tumour." (PMID 27541285, 2017). "However, the percentage of Nestin-positive tumor area markedly decreased in shICAM-1 tumor–bearing mice treated with bevacizumab (34.20 ± 3.66%, p < 0.001) or vehicle (24.10 ± 4.16 %, p < 0.001), compared to GSC11GFP generated tumor treated with bevacizumab respectively." (PMID 29228586, 2017). "Therefore, we performed a detailed expression analysis of the most frequently discussed putative markers of CSCs in PDAC (i.e., CD24, CD44, EpCAM, CD133, and nestin) in both human primary tumor samples and in the respective cell lines derived from those tumors." (PMID 27414409, 2016). "Tumor vessel destruction and tumor-growth inhibition were enhanced by primer dosing of S. typhimurium A1-R in immunocompetent transgenic mice expressing the nestin-driven green fluorescent protein (ND-GFP), which is selectively expressed in nascent blood vessels." (PMID 26431498, 2015). "In addition, the risk of tumor or teratoma formation is still not negligible, since nestin-positive tumor formation was observed 103 days after the transplantation of iPS-derived neurospheres into a mouse model of SCI." (PMID 26696415, 2015). "However, several studies have identified nestin in developing skeletal myoblasts, endothelial cells during reparative angiogenesis and tumour vascularisation, upregulated in the infarcted heart, detected in diverse forms of cancer and a biological role in proliferation and/or migration was reported." (PMID 25139503, 2014). "Tumor vessel destruction and tumor-growth inhibition was enhanced by primer dosing of S. typhimurium A1-R in immunocompetent transgenic mice expressing the nestin-driven green fluorescent protein (ND-GFP), which is selectively expressed in nascent blood vessels." (PMID 25216526, 2014). "Based on these results, we would provided the first demonstration that nestin phenotype exhibited enhanced proliferative properties, and explained scientifically the most important questions of the potential mechanism of nestin action in tumor cell proliferation." (PMID 24498263, 2014). "The identification of proteins mediating recruitment or differentiation of local Nestin(+) cells with potential stem cell character to angiogenic blood vessels may allow the definition of new therapeutic targets to reduce tumor resistance against anti-angiogenic drugs." (PMID 25019063, 2014). "The observation that the Ki-67 protein is expressed during all the active phases of the cell cycle (G1, S, G2, and mitosis), but absent from resting cells, further supports the theory that nestin may be associated with tumor cell proliferation." (PMID 24498263, 2014). "Further studies included immunostaining for nestin with all tumor cells being positive and for synaptophysin showing focally positive tumor cells from all three resections with slightly increased staining in the second tumor sample and larger foci of stained cells in the last resection." (PMID 25563358, 2014). "Moreover, the Nestin+ population significantly contributes to tumor re-growth." (PMID 23771628, 2014).
tumor (continued). "Therefore, further studies evaluating nestin expression in GBM may be more informative when studied in the context of markers more specific to tumor stem cells, including CD133." (PMID 18817556, 2008). "Therefore, nestin expression may have a limited role in identifying the specific cancer stem cell populations within a tumor." (PMID 18817556, 2008). "Nestin-positive (Nes+) tumor cells were detected in all of them, but the proportion of the cells that expressed nestin as well as the intensity of the staining varied from a rare occurrence of Nes+ cells to an overwhelming proportion of cells with high nestin expression." (PMID 18925963, 2008). "Tumor development in the LADY mouse is associated with an increased rate of epithelial proliferation at both six and 16 weeks, increased expression of progenitor cell markers (Notch-1, Nestin) and decreased expression of terminal differentiation markers (Npdc-1 and probasin)." (PMID 17343742, 2007). "Enriched GSC cultures are typically characterized by the expression of stem cell markers such as CD133, Nestin, and SOX2, along with functional assays assessing self-renewal and tumor initiation capacity." (PMID 41008843, 2025). "In gastric cancer, Nestin promotes cell viability and prevents apoptosis by modulating the KEAP1-NRF2 axis, thereby facilitating tumor proliferation and metastasis." (PMID 39941813, 2025). "Regarding tumor capacity to grow, infiltrate and resist apoptosis after PDT, we assessed the expression of vimentin, nestin and SOX2 by immunofluorescence." (PMID 41009470, 2025). "Remarkably, when selecting only the tumour cells in the dataset, we also observed a similar expression pattern in NPC signature (based on SOX2, NES, and ASCL1 genes) and SSTR2, supporting the putative relationship between this NPC population and SSTR2 levels." (PMID 40268793, 2025). "Relative mRNA expression levels of Nestin, OCT4, and CD133 in normal tissues (n = 207) and tumor tissues (n = 163) were obtained from the Gene Expression Profiling Interactive Analysis (GEPIA) database." (PMID 41209573, 2025). "Western blot analysis of tumor tissues revealed elevated expression of CD133, CD15, Nestin, Sox2, and Klf4 in mice implanted with CD133−CD15− cells treated with TMZ compared to controls without TMZ treatment." (PMID 40253386, 2025). "In a subset of tumours, identification of spatial structures in DHG-H3G34mut was found to resemble ‘nests’ of early migratory DCX + interneurons outlined with Nestin + progenitors." (PMID 40986124, 2025). "In 2011, the Svachova team firstly detected nestin in mature CD138+/CD38+ plasma cell (PC) of MM patients, confirming that nestin is a tumor specific marker of CD138+/CD38+ PC in MM patients." (PMID 40799240, 2025). "Exposure of tumor cells to such conditions involves a metabolic adaptation and a canonical upregulation of stem cell genes (CD133, Nestin, SOX2)." (PMID 41562896, 2025). "By categorizing the perivascular region into two distinct zones based on their proximity to tumor cells—far and close—it was found that stemness markers (CD15, CD133, SOX2, NES, and NANOG) exhibited higher expression levels in regions closer to blood vessels." (PMID 41041071, 2025). "Immunohistochemistry revealed both tumor components expressed CD56, Leu-7, PGP9.5, and Nestin, indicating a neural crest origin." (PMID 41179673, 2025). "We compared the expression levels of the CD99, CDKN1A, NES, SOX2, and TUBB3 genes in ES tumor samples and controls consisting of normal muscle tissue." (PMID 38785514, 2024). "APP expression in tumor cells and neurons was confirmed upon double labeling of APP with Nestin and APP with NeuN, and the semiquantitative ratings were confirmed by quantifications of double-labeled cells across 3 regions of interest per case." (PMID 39220249, 2024).